REG4 (regenerating family member 4)
Diseases named in the same sentence as REG4 in open-access papers (continued):
Sharing a sentence is not in itself a finding about the gene and the disease.
Obesity (2 papers, 2021 to 2022). Accumulation of substantial excess body fat. "Reg4 mediates resistance to HFD-induced obesity via IL-35, and the abundance of IAA is low in the peripheral blood of individuals with obesity." (PMID 35074011, 2022). "Here, we found that the gut expression of Reg4 promotes resistance to HFD-induced obesity and the accumulation of IL-35+ cells in adipose tissues." (PMID 35074011, 2022). "We found that these Reg4 KO mice showed more sensitivity to HFD-induced obesity, including a higher body weight, higher fat pad tissue weight, decreased insulin sensitivity and reduced glucose tolerance." (PMID 35074011, 2022). "Taken together, these results show that Reg4 promotes resistance to HFD-induced obesity by increasing the level of IL-35." (PMID 35074011, 2022). "Here, we found Reg4 derived from gut epithelial cells to be related to resistance to HFD-mediated obesity." (PMID 35074011, 2022). "Marked IL-35+ cell accumulation was observed in the adipose tissues, gut tissues and other organs (e.g., spleen) of huREG4IECtg mice, which were resistant to HFD-mediated obesity, whereas fewer IL-35+ cells were observed in Reg4 KO mice than in their control WT littermates." (PMID 35074011, 2022). "We next assessed whether the Reg4-mediated resistance to HFD-induced obesity was dependent on IL-35." (PMID 35074011, 2022). "We first found that gut Reg4 promoted resistance to high-fat diet-induced obesity." (PMID 35074011, 2022). "Indeed, M2 and Treg cells were markedly increased in the adipose tissues of huREG4IECtg mice, which were resistant to HFD-mediated obesity, whereas their levels were significantly decreased in Reg4 KO mice, which were more sensitive to HFD-mediated obesity." (PMID 35074011, 2022). "Since Reg4/REG4 is highly homologous between mice and humans (66% amino acid sequence homology), we also generated transgenic mice expressing REG4 in their intestinal epithelial cells (huREG4IECtg) to further investigate the role of gut Reg4 in HFD-mediated obesity." (PMID 35074011, 2022). "Thus, gut-derived Reg4 (REG4 in humans) is involved in sensitivity to HFD-mediated obesity." (PMID 35074011, 2022). "Since alteration of the gut microbiota is related to the occurrence and development of multiple diseases, such as obesity, we further investigated the role of Reg4 in high-fat diet (HFD)–mediated obesity using Reg4 knockout (KO) mice." (PMID 35074011, 2022). "The levels of inflammatory cytokines related to the development of obesity, such as TNFα, IL-6, and MCP-1, were higher in the adipose tissues of Reg4 KO mice than in those of the control mice." (PMID 35074011, 2022).
pancreatic adenocarcinoma (2 papers, 2009 to 2025). "Targeting circulating REG4 protein appears as a promising adjuvant to current therapies of pancreatic adenocarcinoma, based on gemcitabine administration." (PMID 19834624, 2009).
pancreatic ductal adenocarcinoma (2 papers, 2021 to 2024). An infiltrating adenocarcinoma that arises from the epithelial cells of the pancreas. "In pancreatic ductal adenocarcinomas, tissue expression of REG4 was found to be a useful prognostic marker." (PMID 34577861, 2021).
pseudomyxoma peritonei (2 papers, 2011 to 2014). An appendix cancer that is characterized by progressive accumulation of mucus-secreting tumor cells within the abdomen and pelvis. "On the other hand, REG4 is also abundantly present in mucin-rich cystadenomas of the appendix and in its malignant, disseminated form, pseudomyxoma peritonei, which is notoriously therapy resistant." (PMID 25295732, 2014).
benign ovarian tumors (1 paper, 2015). "REG4 protein expression was detectable in normal ovarian tissue (23.1 %, 6/26), benign ovarian tumors (70 %, 7/10), borderline ovarian tumors (81.8 %, 18/22), primary cancer (50.6 %, 119/235) and metastatic carcinoma in the omentum (61.4 %, 27/44)." (PMID 26077911, 2015). "Here, real-time PCR showed that REG4 mRNA was overexpressed in both benign ovarian tumors and cancers." (PMID 26077911, 2015). "As determined by real-time RT-PCR, REG4 mRNA levels were higher in benign ovarian tumors than those in normal ovarian tissue (P < 0.001); and higher in primary carcinoma than in normal ovarian tissue (P = 0.048)." (PMID 26077911, 2015).
colonic adenomatous polyps (1 paper, 2014). "Increased expression of REG4 was reported in gastric intestinal metaplasia and colonic adenomatous polyps suggesting a role in premalignant lesions." (PMID 24533081, 2014).
enteritis (1 paper, 2022). Inflammation of the small intestine. "The activating transcription factor 2 (ATF2) targeted the REG4 promoter to induce REG4 expression during enteritis." (PMID 36172286, 2022).
gynecological cancers (1 paper, 2025). "Additionally, REG4 mRNA expression has been identified as a potential biomarker for gynecological cancers or a therapeutic target." (PMID 39944833, 2025).
Hepatic steatosis (1 paper, 2024). Steatosis is a term used to denote lipid accumulation within hepatocytes. "The expression of Reg4 can reduce intestinal fat absorption to protect mice from high-fat diet-induced hepatic steatosis, increased fat accumulation, and insulin resistance." (PMID 38915894, 2024).
hyperplastic polyp (1 paper, 2014). A polyp found mainly in the stomach and colon. "In contrast to the other proteins, intense immunostaining for REG4 was found in SSA/Ps, hyperplastic polyps and adenomatous polyps and weak to intermediate staining in control colon." (PMID 24533081, 2014).
Hypertension (1 paper, 2024). The presence of chronic increased pressure in the systemic arterial system. "The risk of hypertension is related to the NRBP1, REG4, CCNE2, and KCNJ11 genes." (PMID 38915894, 2024).
intrahepatic cholangiocarcinoma (1 paper, 2016). A carcinoma that arises from the intrahepatic bile duct epithelium in any site of the intrahepatic biliary tree. "Furthermore, tissue expressions of Reg1A, Reg1B, and Reg4 could differentiate metastatic PDAC in the liver from intrahepatic cholangiocarcinoma with 92% sensitivity and 95% specificity." (PMID 27788482, 2016).
myocardial infarction (1 paper, 2023). Gross necrosis of the myocardium, as a result of interruption of the blood supply to the area, as in coronary thrombosis. "Recently, it has been reported that Reg4 protein along with Reg3 protein directs accumulation of functionally distinct macrophages subsets after myocardial infarction." (PMID 36720768, 2023).
ovarian epithelial tumor (1 paper, 2016). A benign, borderline, or malignant tumor that originates from the surface epithelium of the ovary. "Immunohistochemical staining of REG4 in ovarian epithelial tumor tissues." (PMID 26981633, 2016).
ovarian tumors (1 paper, 2016). "REG4 expression was further validated with qRT-PCR and western blotting from fresh frozen ovarian tumor tissue samples originating from serous and mucinous subtypes." (PMID 26981633, 2016). "The specific mucinous lineage expression of REG4 within ovarian neoplasms was demonstrated by several ways." (PMID 26981633, 2016). "The first evidence was obtained from in silico analyses, which indicated very specific mRNA expression profile of REG4 in mucinous cancers among various ovarian tumor subtypes." (PMID 26981633, 2016). "The in silico analysis indicated specific expression of REG4 mRNA in mucinous histotype of ovarian tumors." (PMID 26981633, 2016). "REG4 expression pattern was studied in TMAs containing clinical samples from ovarian tumors with different histotypes." (PMID 26981633, 2016). "In order to validate these data, REG4 mRNA and protein expression was studied in samples from mucinous (MUC) and high-grade serous (SER) ovarian tumors." (PMID 26981633, 2016).
pneumonia (1 paper, 2024). An acute, acute and chronic, or chronic inflammation focally or diffusely affecting the lung parenchyma, caused by an infection in one or both of the lungs (by bacteria, viruses, fungi, or mycoplasma.). "Therefore, Reg4 may be a promising therapeutic agent for treating P. aeruginosa-associated pneumonia." (PMID 38501823, 2024).
pulmonary fibrosis (1 paper, 2024). Chronic progressive interstitial lung disorder characterized by the replacement of the lung tissue by connective tissue, leading to progressive dyspnea, respiratory failure, or right heart failure. "Furthermore, Reg4 treatment inhibited pulmonary fibrosis, which is characterized by decreasing Ashcroft scores in PAO1-infected mice." (PMID 38501823, 2024).
Salmonella Infections (1 paper, 2025). Infections with bacteria of the genus SALMONELLA. "The α-Defensin and Reg4 deficit may be associated with Salmonella infection pathway enrichment in enterocyte clusters 1-3." (PMID 40756359, 2025).
cancer (53 papers, 2009 to 2025). A tumor composed of atypical neoplastic, often pleomorphic cells that invade other tissues. "REG4 up-regulation has been associated with cancer in the GI-tract including pancreas where it stimulates proliferation and inhibits apotosis." (PMID 37064098, 2023). "Regenerating islet-derived type 4 (REG4) is a member of the calcium-dependent lectin gene superfamily and it was associated with a relatively unfavorable prognosis in various cancers, including CRC." (PMID 36831448, 2023). "The current review will focus on the clinical significance and underlying mechanisms of REG4 in various human cancers and highlight its potential applicability for diagnostic, prognostic and therapeutic approaches." (PMID 33489872, 2020). "In this review, we systematically summarize the advances about the clinical significance, biological functions, and mechanisms underlying REG4 in cancer to provide new directions for future cancer research." (PMID 33489872, 2020). "REG4 is associated with a relatively unfavorable prognosis and clinicopathologic features in cancers, including advanced tumor and nodal stage, histological differentiation, and liver and peritoneal metastasis." (PMID 33489872, 2020). "Of these genes, regenerating islet-derived family member 4 (REG4, which encodes Reg IV protein) is a candidate gene for cancer-specific expression." (PMID 23133598, 2012). "Association between REG4 levels and carcinoma has been under study in both serum and tissues." (PMID 25295732, 2014). "Thus, REG4 may be a potential diagnostic and prognostic biomarker as well as a candidate therapeutic target in cancer patients." (PMID 33489872, 2020). "REG4 is widely expressed in gastrointestinal tumors and usually defines cancer subtypes with intestinal and goblet-like differentiation and with poor prognosis." (PMID 39632825, 2024). "REG4 is known as a member of the calcium-dependent lectin gene superfamily, which aberrantly expresses in multiple cancers including PDAC." (PMID 38827297, 2024). "The REG4 secreted by cancer cells promotes macrophage polarization to M2, promoting tumor growth and distant metastasis." (PMID 39256888, 2024). "Among the seven subclusters of cancer cells, cancer cell subcluster 1 specifically expressed high levels of REG4, FCGBP and MUC2, which are considered markers of goblet cells." (PMID 36690709, 2023). "A body of evidence has shown that REG4 was markedly related to chemoresistance, migration, and invasion of cancer cells." (PMID 36172286, 2022). "Adenomatous and cancer cells positive for REG4 mRNA exhibited enterocyte-like, mucus-secreting, or undifferentiated features, in agreement with observations in the stomach." (PMID 36172286, 2022). "The PC2 cluster showed high expression in TFF3 and REG4, where cells were obtained from the cancer tissue of intestinal patients." (PMID 35087207, 2022). "This was also evidenced by the positive correlation of cancer stem markers with REG4 in intestinal tumors from APCmin+/KrasG12D LA2 mice." (PMID 36172286, 2022). "In human diffuse-type gastric carcinoma cells (OCUM‐2MLN and HSC‐39), regenerating islet‐derived family member 4 (REG4) is upregulated in ALDH1+ cancer-initiating cells." (PMID 35310914, 2022). "In this review, we summarized the structure, biological functions, and effects of REG4 on inflammation and cancer." (PMID 36172286, 2022). "Our in vitro data shows that Reg4-CD44ICD signaling regulates proliferation and survival of the cancer stem cells, hence providing a unifying explanation for poor clinical outcomes with Reg4 and CD44/CD44ICD." (PMID 33659040, 2021). "REG4 expression was significantly higher in the cancers of right colon than that in cancers of left colon and rectum (p = 0.002)." (PMID 34577861, 2021). "In this study, we also found a significant association between Reg4, CD44, and CD44ICD; demonstrating for the first time that this pathway is biologically relevant outside of cancer cell lines alone." (PMID 33659040, 2021).
cancer (continued). "The clinicopathological implications of REG4 expression have been studied in various malignant tumors." (PMID 34577861, 2021). "Another study demonstrated that REG4-induced EGFR/Akt pathway activation promotes cancer cell progression directly and polarization of macrophages to M2 phenotype." (PMID 33489872, 2020). "High expression of REG4 predicts poor prognosis and drug-resistance by promoting cancer cell proliferation, invasion and anti-apoptosis." (PMID 33489872, 2020). "Tumor-secreted REG4 can change the tumor microenvironment to facilitate cancer cell growth and metastasis by promoting macrophage polarization to M2 via activation of the EGFR/Akt/CREB pathway." (PMID 33489872, 2020). "Another study also indicated that targeting REG4 in aldehyde dehydrogenase 1 (ALDH1) positive cancer-initiating cells regulates the tumorigenic capacity of diffuse-type gastric carcinoma-initiating cells inhibited by GSK-3β." (PMID 33489872, 2020). "The intensity of staining for Reg1A and Reg1B in these cancer cells was much stronger than that of Reg4, despite the fact that Reg4 had previously been reported as a biomarker of PDAC." (PMID 27788482, 2016). "The interesting part of REG4 is that it is able to activate EGFR pathway, in the meantime, REG4 mRNA can be induced by some EGFR ligands, which suggests that a positive feedback loop of REG4 regulation is likely to exist in cancer tissues." (PMID 27036049, 2016). "REG4 expression was examined in normal ovarian tissue, benign and borderline tumors, and cancers by immunohistochemistry or real-time PCR." (PMID 26077911, 2015). "REG4 mRNA levels were higher in benign tumors and primary cancer compared to those in normal ovarian tissue (P < 0.05) while, REG4 protein expression was higher in all three tumor types than that in normal ovarian tissue (P < 0.05)." (PMID 26077911, 2015). "Several reports suggest the oncogenic role of REG4 in the development of cancer in the gastrointestinal tract." (PMID 25295732, 2014). "Upon secretion by tumor cells, reg4 would activate, probably through specific receptors, intracellular pathways that favor cancer progression." (PMID 19834624, 2009). "reg4 gene increased copy number was particularly interesting because its expression was previously involved in the aggressiveness of several cancers, including pancreas." (PMID 19834624, 2009). "Notably, genes such as TFF3, CLDN3, CDH17, and REG4 exhibited specific expression in tumor cells, linking to the cancer progression." (PMID 40452847, 2025). "REG4 upregulation in the tumor may create additional cancer stem cell (CSC) niches, facilitating the growth of the aggressive subpopulation of LGR5-positive CSCs." (PMID 38066386, 2024). "We found knockdown of REG4 or SPINK1 do alter a series of cancer-related characteristics in PDAC." (PMID 38827297, 2024). "We conclude that REG4 may be employed as a biomarker of tumorigenesis, subsequent progression and poor prognosis of cancer, and may be a useful target for gene therapy." (PMID 36172286, 2022). "Moreover, REG4 protein or conditioned medium promotes M2 polarization in cultured macrophages and supports cancer cell proliferation in vitro." (PMID 35742884, 2022). "In malignant tumor cells, REG4 promotes proliferation and inhibits apoptosis." (PMID 34577861, 2021). "In the gallbladder, REG4 is expressed in the intestinal metaplastic epithelium and cancer cells." (PMID 34577861, 2021). "REG4 can also promote cancer cell proliferation and anti-apoptosis via other mechanisms." (PMID 33489872, 2020). "REG4 promotes cancer stem cells properties via Wnt/β-catenin pathway." (PMID 33489872, 2020). "The ADAM9/REG4/p21Cip1/WAF1 pathway contributes to cancer cell division and drug resistance." (PMID 33489872, 2020). "Of these, REG4 is the most frequently observed member and has been characterized as a key regulator in the initiation, differentiation, and progression of various human cancer cell types." (PMID 33489872, 2020).